DECR1 (2,4-dienoyl-CoA reductase 1)
Description:
Auxiliary enzyme in the beta-oxidation of mono- and polyunsaturated fatty acids (Probable). Together with the Enoyl-CoA delta isomerase 1 (ECI1) and the Delta(3,5)-Delta(2,4)-dienoyl-CoA isomerase (ECH1) they allow reentrance of the enoyl-CoA into the beta-oxidation cycle. It participates in the metabolism of unsaturated fatty enoyl-CoA esters having double bonds in both even- and odd-numbered positions in mitochondria. Acts primarily on polyunsaturated fatty acids (Probable). Catalyzes the NADP-dependent reduction of 2,4-dienoyl-CoA to yield trans-3-enoyl-CoA. Based on its established catalytic mechanism, it is predicted to act also on other fatty acids besides those tested experimentally (Probable).
Synonyms: DECR; SDR18C1; NADPH
Tractability: Small molecule: a structure with a bound ligand is known; it has a high-quality binding pocket. PROTAC: ubiquitination databases record sites on it; its protein half-life has been measured.
Target class: Enzyme; Oxidoreductase
Gene: Protein-coding gene on chromosome 8 (90,001,330 to 90,053,633, forward strand). Ensembl gene ENSG00000104325.
Subcellular location: Mitochondrion
Subcellular location (Human Protein Atlas): Mitochondria; Cytosol
Pathways (Reactome):
Metabolism: mitochondrial fatty acid beta-oxidation of unsaturated fatty acids
Gene Ontology:
Molecular function: 2,4-dienoyl-CoA reductase (NADPH) activity; identical protein binding; NADPH binding
Biological process: fatty acid beta-oxidation; positive regulation of cold-induced thermogenesis
Cellular component: catalytic complex; mitochondrion; nucleus; mitochondrial matrix
Genetic constraint (gnomAD): Loss-of-function variants: 36 observed, 30.33 expected, observed/expected ratio (o/e) 1.19, 90% interval 0.91 to 1.57. The upper end of that interval is the gene's LOEUF score, 1.57, which puts it in group 6 of 6, group 1 being the genes least tolerant of losing a copy. Missense variants: 380 observed, 365.9 expected, observed/expected ratio (o/e) 1.04, 90% interval 0.95 to 1.13. Synonymous variants: 134 observed, 126.54 expected, observed/expected ratio (o/e) 1.06, 90% interval 0.92 to 1.22.
Gene-disease validity (ClinGen):
ClinGen rates the evidence that DECR1 causes each of these diseases.
progressive encephalopathy with leukodystrophy due to DECR deficiency (inheritance undetermined): No Known Disease Relationship.
Homologues: Orthologues: chimpanzee DECR1 (99% identical), macaque DECR1 (96% identical), dog DECR1 (88% identical), pig DECR1 (86% identical), guinea pig DECR1 (83% identical), rat Decr1 (83% identical), mouse Decr1 (82% identical), tropical clawed frog decr1 (69% identical), zebrafish decr1 (66% identical), Caenorhabditis elegans decr-1.1 (47% identical), Caenorhabditis elegans decr-1.3 (43% identical), Caenorhabditis elegans decr-1.2 (41% identical). Paralogues in human: DECR2 (30% identical).
Diseases named in the same sentence as DECR1 in open-access papers:
DECR1 is named in the same sentence as 71 diseases in open-access papers, as found by Europe PMC text mining. Sharing a sentence is not in itself a finding about the gene and the disease. The quoted sentences say what the papers report.
prostate carcinoma (13 papers, 2020 to 2025). A carcinoma that arises from epithelial cells of the prostate gland. "DECR1 knockdown-induced cell death is mediated by ferroptosis caused by accumulation of PUFAs in prostate cancer." (PMID 39872359, 2022). "Mechanistically, we show that DECR1-deficient prostate cancer cells accumulate higher levels of polyunsaturated lipids." (PMID 32427840, 2020). "Furthermore, knocking down 2,4-dienoyl–CoA reductase (DECR1), an enzyme involved in fatty acid oxidation, causes cellular accumulation of PUFAs and enhances mitochondrial oxidative stress and lipid peroxidation in human prostate cancer." (PMID 35192544, 2022). "When DECR1 is deleted, castration-resistant prostate cancer cell lines are more likely to undergo ferroptosis due to endoplasmic reticulum stress induction." (PMID 41169393, 2025). "Another study revealed that DECR1 knockdown induces ER stress and sensitizes castration-resistant prostate cancer (CRPC) cells to ferroptosis, highlighting the importance of DECR1 in tumor progression and the development of therapeutic resistance." (PMID 40083691, 2025). "Knocking out DECR1 induces ER stress and sensitizes castration-resistant prostate cancer cells to ferroptosis both in vitro and in vivo." (PMID 38908072, 2024). "Previous studies have reported that elevated DECR1 levels in prostate cancer promote the oxidation of PUFA, leading to a reduction in intracellular PUFA content and the subsequent development of ferroptosis resistance 24,25." (PMID 39629121, 2024). "DECR1 inhibits ferroptosis in prostate cancer, which is driven by the reduction of scavenging and the iron-dependent accumulation of ROS44." (PMID 37031243, 2023). "A similar conclusion was independently arrived at by a study showed that DECR1 knockout induces ER stress and sensitivity to ferroptosis in castration-resistant prostate cancer cells." (PMID 39872359, 2022). "DECR1 can cause PUFA depletion in prostate cancer by encoding the rate-limiting enzyme of PUFA oxidation, thus protecting prostate cancer from ferroptosis." (PMID 34869390, 2021). "In silico analysis of the cancer genome atlas (TCGA) dataset revealed that DECR1 expression was frequently dysregulated in prostate cancer, at both gene and transcript levels." (PMID 32427840, 2020). "As an androgen receptor (AR) target gene with negative regulatory activity, DECR1 might support human prostate cancer (PCa) cell survival and resistance to AR targeting therapies." (PMID 36467089, 2022). "Decr1 is an auxiliary enzyme of fatty acid beta-oxidation located in mitochondria and has been reported to participate in lipid modulation and mitochondrial oxidative stress in prostate cancer." (PMID 35872903, 2022). "We next assessed the clinical relevance of DECR1 in prostate cancer." (PMID 32427840, 2020). "Interestingly, acute treatment of multiple AR-proficient prostate cancer cell lines with any of the AR inhibitors was sufficient to modulate DECR1 expression and transient silencing of DECR1 potentiated the effect of enzalutamide in C4-2 cells, a CRPC derivative of LNCaP." (PMID 32427840, 2020). "2,4-Dienoyl-CoA reductase 1 (DECR1), which is involved in PUFA beta-oxidation in the mitochondria, is notably overexpressed in prostate cancer." (PMID 38908072, 2024). "It has been reported that DECR1 knockdown inhibits PUFA β-oxidation and leads to accumulation of PUFAs in the LNCaP prostate cancer cell line." (PMID 39872359, 2022). "In contrast, prostate cancers exhibit enhanced fatty acid oxidation (FAO) and increased expression of 2,4 dienoyl-CoA reductase 1 (DECR1), a rate-limiting enzyme in β-oxidation of PUFA, in malignant prostate tissues compared to nonmalignant tissues." (PMID 33499222, 2021).
prostate carcinoma (continued). "2,4-Dienoyl-CoA reductase 1 (DECR1) is the rate-limiting enzyme in a PUFA β oxidation auxiliary pathway, and its knockdown induces the significant accumulation of phospholipid hydroperoxides, increases the levels of mitochondrial oxidative stress, and induces ferroptosis in prostate cancer cells." (PMID 40083691, 2025). "DECR1-dependent PUFA remodeling enhances mitochondrial oxidative stress to promote lipid peroxidation and ferroptosis, which is a negatively regulated by androgen receptor, thus suggesting ferroptosis induction by targeting androgen receptor signaling in human prostate cancer." (PMID 38908072, 2024).
breast carcinoma (8 papers, 2019 to 2025). "These aberrations highlighted well-known breast cancer-associated genes, such as MDM4, ZNF595, FGFR4, HIST1H1B, TPD52, DECR1, GRB7, and JUP55." (PMID 40162205, 2025). "DECR1 is sufficient to restrict breast cancer cell proliferation through its ability to limit the extent of oncogene expression and reduce the stable level of de novo fatty acid synthesis." (PMID 39403185, 2024). "DECR1 expression is significantly reduced in numerous breast tumor models and in primary breast cancer." (PMID 39403185, 2024). "In the other hand, DECR1 was recognized as a cancer suppressor in HER2-positive breast cancer." (PMID 35053570, 2022). "2,4-Dienoyl-CoA reductase 1 (DECR1) can limit the rate of PUFA oxidation, and its expression is significantly increased in prostate tumors and castration-resistant mice, but the opposite is observed in breast cancer." (PMID 37061523, 2023).
prostate tumor (5 papers, 2020 to 2025). "DECR1 mRNA expression level was significantly higher in prostate tumour samples than in normal adjacent tissues, and high DECR1 expression was associated with significantly reduced patient disease-free survival." (PMID 32427840, 2020). "CSNK2A2 has been reported as a marker of PCa progression and prognosis, while DECR1 acts as an androgen-repressed survival factor that regulates PUFA oxidation to protect prostate tumor cells from ferroptosis." (PMID 40626556, 2025). "The marked overexpression of DECR1 in prostate tumors across multiple clinical cohorts, potentially coupled to PUFA-related dietary interventions, may lend further selectivity to targeting strategies." (PMID 32686647, 2020).
Hypoglycemia (4 papers, 2009 to 2024). A decreased concentration of glucose in the blood. "Reported Decr1 knockout mice manifested fasting-related hypoglycemia, hepatic microvesicular steatosis, an altered fatty acid profile in liver and serum, and inability to maintain a normal body temperature during cold exposure." (PMID 39277655, 2024). "This conclusion is supported by the clinical findings in Decr1 knockout mice, which developed microvesicular SLD upon fasting, hypoglycemia under metabolic stress, and fatal hypothermia upon acute cold challenge." (PMID 39277655, 2024).
Obesity (4 papers, 2013 to 2025). Accumulation of substantial excess body fat. "Interactome network analysis of the lower expressed genes in FTO obesity-risk genotype suggests that under normal conditions, DECR1 (dienoyl-CoA reductase), LIPE, LDHB, SOD2, ATP5B, and J are central elements in maintaining connectivity." (PMID 32316277, 2020). "The proteomic results showed that Decr1 protein may be a potential diagnostic and therapeutic target for obesity‐induced cardiovascular disease." (PMID 40052435, 2025). "Neither hepatomegaly nor abnormal transaminase values were present in their elder brother with class II obesity and sonographic evidence of hepatic steatosis who does not carry the DECR1 variant." (PMID 39277655, 2024).
breast tumors (3 papers, 2021 to 2026). "DECR1 is overexpressed in breast tumors and correlates with poor patient outcome; its knockdown markedly suppresses proliferation and migration by modulating ferroptosis." (PMID 41517855, 2026). "Moreover, ectopic expression of DECR1 in ErbB2/Neu-induced breast tumor cells is sufficient to reduce ErbB2/Neu expression levels and impair breast tumor growth." (PMID 39403185, 2024).
diabetes (3 papers, 2009 to 2025). "HE and WGA staining revealed that Decr1‐overexpressed mice exhibited exacerbated cardiomyocyte area caused by diabetes." (PMID 40052435, 2025). "Functionally, PDK4 downregulation attenuated HG/HP‐induced hypertrophy, apoptosis, and oxidative damage in cardiomyocytes, highlighting the pathogenic role of Decr1 as a key mediator of diabetes‐induced cardiac injury." (PMID 40052435, 2025). "Conversely, cardiac‐specific overexpression of Decr1 exacerbated diabetes‐induced cardiac remodelling and dysfunction." (PMID 40052435, 2025). "In vivo and in vitro studies disclosed that deletion of Decr1 in cardiomyocytes alleviated cardiac abnormalities in diabetes, while overexpression of Decr1 exacerbated DCM." (PMID 40052435, 2025). "In summary, our study demonstrates that Decr1 serves as a potential therapeutic target for mitigating diabetes‐related cardiac complications." (PMID 40052435, 2025). "Assessment of cardiac fibrosis in mice using Sirius Red staining showed that downregulation of Decr1 afforded a protection against diabetes‐evoked myocardial fibrosis." (PMID 40052435, 2025). "Cardiac‐specific knockdown of Decr1 significantly ameliorated diabetes‐induced cardiac dysfunction, as evidenced by improved left ventricular EF and FS." (PMID 40052435, 2025). "This study highlights the essential role of Decr1 in cardiac abnormalities in the context of diabetes." (PMID 40052435, 2025). "Upregulation of Decr1 in diabetic hearts propelled us to investigate whether or not cardiac‐specific knockdown of Decr1 could ameliorate diabetes‐related cardiac pathologies." (PMID 40052435, 2025).
heart failure (3 papers, 2021 to 2025). Inability of the heart to pump blood at an adequate rate to meet tissue metabolic requirements. "Given the role of Decr1 in fatty acid metabolism, future studies could explore the potential benefits of Decr1 inhibitors in other cardiometabolic diseases, such as obesity‐related cardiomyopathy or heart failure with preserved ejection fraction (HFpEF)." (PMID 40052435, 2025). "REN is an established biomarker having prognostic significance in heart failure, whereas DDX58 and DECR1 are relatively new proteins identified in the present study in association with congestion and HF." (PMID 40985000, 2025).
bladder cancer (2 papers, 2022). "We obtained the results of immunohistochemical staining of ACOT13, CYP1, DECR1, IL4I1, and SCD in both normal tissues and bladder cancer tissues and found that the expression of CYP1 was higher in normal tissues, while other genes were higher in tumor tissues than in normal tissues." (PMID 36131793, 2022).
cardiac hypertrophy (2 papers, 2020 to 2025). "Additionally, Decr1 deficiency reduced cardiac hypertrophy, fibrosis, apoptosis, and oxidative stress in T2D mice." (PMID 40052435, 2025).
hyperglycaemia (2 papers, 2016 to 2025). "In summary, these findings highlight the significant role of cardiac Decr1 in regulating hyperglycaemia‐induced myocardial damage." (PMID 40052435, 2025). "Hyperglycemia led to cardiomyocyte enlargement in diabetic mouse heart, as observed in haematoxylin and eosin (H&E) and WGA staining, but these changes were notably reversed by deficiency of Decr1." (PMID 40052435, 2025). "Overall, Decr1 may be a positive regulator of PDK4, leading to hyperglycemia‐induced cardiomyocyte injury." (PMID 40052435, 2025).
liver disease (2 papers, 2024). "These patients may represent the first individuals with DECR1 deficiency, then defining within MASLD an autosomal-recessive entity, well corresponding to the reported steatotic liver disease in Decr1 knockout mice." (PMID 39277655, 2024). "Interestingly, analysis of the Gepliver database revealed consistent upregulation of DECR1 expression in various liver diseases, including NAFLD, liver cirrhosis, and HCC." (PMID 39629121, 2024).
Atrophy (1 paper, 2021). Any weakening or degeneration, especially through lack of use. "The other proteins Gapdh, Cat, Vegfa, Decr1, Cs, and Suclg1 are mostly important links in redox and energy metabolism pathways, and they may be potential targets in denervated muscle atrophy for treatment." (PMID 34193880, 2021).
cardiac arrhythmia (1 paper, 2022). Any disturbances of the normal rhythmic beating of the heart or MYOCARDIAL CONTRACTION. "We validated some key genes by real-time PCR and found Decr1 (an enzyme which participates in fatty acid β-oxidation), Calm2 (associated with cardiac arrhythmias), and Ddit3 (a proapoptotic transcription factor) expressed a statistically significant increase when compare with the control group." (PMID 35464763, 2022).
cervical cancer (1 paper, 2024). A primary or metastatic malignant neoplasm involving the cervix. "High levels of DECR1 (2,4-Dienoyl-CoA reductase) serves to enhance lipolysis and the release of fatty acid energy stores to support cervical cancer cell growth." (PMID 38355626, 2024).
diabetic cardiomyopathy (1 paper, 2022). Diabetic cardiomyopathy is a disorder of the heart muscle in people with diabetes. "The 2,4-dienoyl-CoA reductase 1(DECR1) gene has been reported as one of the most significantly upregulated hub genes in diabetic cardiomyopathy, but further validation has not been performed." (PMID 35971449, 2022).
Hepatitis B (1 paper, 2023). "For example, for Hepatitis B, predicted gene #2, F5; predicted gene #6, DECR1; predicted gene #7, SLC27A5, and predicted gene #9, DPP4, are all associated with liver function by the GeneCards platform." (PMID 36791052, 2023).
lactic acidosis (1 paper, 2020). Metabolic acidosis characterized by the accumulation of lactate in the body. "Human DECR1 deficiency is lethal, with patients exhibiting hypocarnitinemia, decreased cellular oxygen consumption, increased lactic acidosis, and unusual accumulation of FA intermediates in urine and blood due to incomplete β-oxidation." (PMID 32686647, 2020).
lung adenocarcinoma (1 paper, 2025). A carcinoma that arises from the lung and is characterized by the presence of malignant glandular epithelial cells. "Compared with lung adenocarcinoma cell lines A549 and H1975, the expression of DECR1 in human normal lung epithelial cells BEAS-2B was significantly lower." (PMID 41169393, 2025). "The research results indicated that knocking down DECR1 can restrain the migration and proliferation abilities of lung adenocarcinoma cells and simultaneously accelerate their apoptosis, which is consistent with the results of the model." (PMID 41169393, 2025). "It is highly likely that DECR1 promotes the occurrence and development of lung adenocarcinoma and can be further studied as an effective biomarker." (PMID 41169393, 2025). "In vitro validation demonstrated that knockdown of DECR1 significantly suppressed lung adenocarcinoma cell proliferation and migration, and promoted cell apoptosis (P < 0.05)." (PMID 41169393, 2025). "In addition, the apoptosis experiment indicated that knocking down DECR1 increased the apoptosis of lung adenocarcinoma cell A549 and inhibited cell survival." (PMID 41169393, 2025). "qRT-PCR was used to evaluate the relative expression levels of DECR1 in human normal lung epithelial cells BEAS-2B and lung adenocarcinoma cell lines A549 and H1975." (PMID 41169393, 2025).
metastatic prostate carcinoma (1 paper, 2020). A carcinoma that arises from the prostate gland and has spread to other anatomic sites. "In addition to that, we demonstrated that high expression of DECR1 in primary and metastatic prostate cancer correlates with unfavourable patient survival outcomes." (PMID 32427840, 2020).
mouth ulcers (1 paper, 2023). "The proteins encoded by eight genes (PMEL, ARFIP1, FAM213A, GLUL, CADM2, FAIM3, RIPK2, and DECR1) have only one SNP instrumental variable and have a association with mouth ulcers using the Wald ratio method." (PMID 37369724, 2023).
myocardial infarction (1 paper, 2024). Gross necrosis of the myocardium, as a result of interruption of the blood supply to the area, as in coronary thrombosis. "Increasing DECR1 levels after myocardial infarction ameliorates mitochondrial structural damage and bioenergetic dysfunction." (PMID 39765837, 2024).
sarcopenia (1 paper, 2026). Progressive decline in muscle mass due to aging which results in decreased functional capacity of muscles. "Thus, DECR1, HSD17B7 (AUC > 0.85), and OPN3 (AUC > 0.85) may serve as strong diagnostic biomarkers for sarcopenia." (PMID 41460756, 2026).
schizophrenia (1 paper, 2024). A major psychotic disorder characterized by abnormalities in the perception or expression of reality. "In fatty acid synthesis, DECR1 was upregulated in schizophrenia but downregulated in ketosis, whereas ACACB and HADH were upregulated in both." (PMID 39125835, 2024).
steatosis (1 paper, 2024). Increased lipid within the cytoplasm of cells. "Two siblings have hepatomegaly, elevated serum transaminase activity, and steatosis and harbor a homozygous DECR1 splice-site variant, c.330+3A>T." (PMID 39277655, 2024).